MT1G (metallothionein 1G)
Diseases named in the same sentence as MT1G in open-access papers (continued):
Sharing a sentence is not in itself a finding about the gene and the disease.
cancer (continued). "We also identified the upregulation of DAZL and ANXA3 (data not shown), genes previously reported to be induced by 5-aza-dC, NDN, reported to be imprinted, and MT1G, reported to be methylated in other cancers." (PMID 22984426, 2012). "Moreover, the CPTAC database analysis indicated that MT1G’s protein level was lower in ccRCC cancer than in normal adjacent tissue." (PMID 38906969, 2024). "Metallothionein 1G (MT1G), observed in various cancers, may serve as a potential therapeutic target for OS." (PMID 38747739, 2024). "In our study, we found that MT1G is enriched in certain cancer pathways as well as cytokine signaling pathways, with a typical representative being the PI3K-Akt signaling pathway, which is a pro-mitotic signaling pathway, and it is also associated with angiogenesis." (PMID 38747739, 2024). "This protective effect of MT1G on cancer cells contributes to the development of drug resistance." (PMID 39534872, 2024). "MT1G upregulation could promote cancer progression by protecting HCC cells from sorafenib and inhibiting ferroptosis mediated by lipid peroxidation." (PMID 36204178, 2022). "Knockdown of MT1G led to increased expressions of cancer stemness markers." (PMID 33537082, 2021). "Activin A has been reported as a key player in regulating cancer stemness and chemoresistance 9,10, hence we speculated that MT1G might suppress PDAC stemness by limiting activin A secretion." (PMID 33537082, 2021). "These two characteristics are linked with CSCs, however MT1G involvement in the regulation of cancer stemness has not been fully validated." (PMID 33537082, 2021). "In this study, we identified MT1G as a critical molecule related with PDAC cancer stemness." (PMID 33537082, 2021). "Furthermore, Nrf2 can promote the expression of metallothionein 1G (MT1G), an important negative regulator of ferroptosis, through the cystathionase pathway, leading to the resistance of cancer cells to sorafenib." (PMID 34970553, 2021). "Additionally, we found that nearly half of these 21 edges involved a protein of the Metallothionein family (i.e. MT1H, MT2A, MT1HL1, MT1X and MT1G), involved in the regulation of transcription factors and in cancers." (PMID 34197603, 2021). "The findings from the present study are also helpful for a better understanding of the link between trace elements and HCC by suggesting the possible role of serum Cu concentrations and of MT1G/MT1H promoter methylation in cancer tissues as prognostic factors in HCC." (PMID 33585212, 2020). "MT1G was not significantly linked with prognosis in pan-cancer." (PMID 40432442, 2025). "Unfortunately, MT1G involvement in the regulation of cancer stemness has not been fully validated and the underlying mechanism remains unclear." (PMID 33537082, 2021). "For the mechanism how MT1G is methylated in the drug resistance-induced cancer stem cells, we considered that long term exposure to chemo drugs such as gemcitabine might induce DNMT upregulation in drug resistant cells, as DNMT is a key player in mediating tumor suppressor genes methylation." (PMID 33537082, 2021). "As MT1G levels increased, CPT1B levels progressively decreased in different grades of ccRCC cancer patients, accompanied by lipid droplet accumulation." (PMID 38906969, 2024). "Several metallothionein genes, including MT1E, MT1G and MT1M were upregulated in the SPINK1 general cancer pathway." (PMID 35369880, 2022). "Strikingly, members of the metallothionein family, including MT1M, MT1H, MT1G, MT1F, MT1E, MT1X, and MT1A, were significantly downregulated in cancer cells." (PMID 35967424, 2022). "Of which, the top 20 differential expressed genes (DEGs) were mainly related to the progression of malignant tumors, including SYT12, CLDN10, COL9A3, SFRP1, MT1G, MTIH, etc.." (PMID 36253446, 2022). "Recently, MT1 isoforms, in particular MT1M and MT1G, were suggested as possible biomarkers for HCC and other human cancers." (PMID 33585212, 2020).
cancer (continued). "While down-regulated genes were associated with GO categories such as cellular response to zinc ion where members of metallothionein family (MT1M, MT1H, MT1X, MT1G, and MT1F) play important roles in carcinogenesis of various cancer types." (PMID 32849813, 2020). "Activation of NRF2 axis in cancer cells triggers the induction of multiple anti-ferroptotic genes, including SLC7A11, ATP binding cassette subfamily C member 5 (ABCC5), metallothionein 1G (MT1G), FSP1, CBS, and superoxide dismutase 2 (SOD2)." (PMID 39624080, 2024). "The other genes (MT-1G and THY1) which were found to be hypomethylated in this study have not been previously investigated in SSc and SLE, though are known to be hypermethylated in cancer." (PMID 25986394, 2015). "Metallothionein-1G (MT-1G), a member of the MT family, was recently identified as a negative regulator of ferroptosis and a positive regulator of sorafenib resistance in HCC and could be used as a biomarker to explore the impact of Sorafenib on redox metabolism of cancer cells." (PMID 35663406, 2022). "In addition to the commonly known hypomethylated genes in SLE and SSc, there are other hypomethylated genes (such as MT-1G and THY-1) that have not previously been investigated in SLE and SSc though are known to be hypermethylated in cancer." (PMID 25986394, 2015).
infection (4 papers, 2015 to 2023). The state of being infected such as from the introduction of a foreign agent such as serum, vaccine, antigenic substance or organism. "At every 24 hours within 4 days after lentiviruses infection of SiHa and CaSki, we used Q-PCR to analyze the expression of E6, E7, DNA methyltransferase genes (DNMT1, DNMT3A, DNMT3B and DNMT3L), and tumor suppressor genes (MT1G, NMES1, RRAD, SFRP1, SPARC and TFPI2)." (PMID 26329329, 2015).
MT1G also shares sentences with these, for which no sentence is quoted: breast carcinoma (2 papers); periodontal disease (2); amyloidosis (1); bladder cancer (1); cardiovascular diseases (1); chronic hepatitis B (1); Cirrhosis (1); diffuse large B-cell lymphoma (1); Down syndrome (1); esophageal squamous cell carcinoma (1); glioblastoma (1); liver neoplasm (1); lung fibrosis (1); nephrotic syndrome (1); nutritional deficiency (1); renal papillary cell carcinoma (1); retinal disease (1).